STMN1 (stathmin 1)
Diseases named in the same sentence as STMN1 in open-access papers (continued):
Sharing a sentence is not in itself a finding about the gene and the disease.
ovarian carcinoma (continued). "Conversely, an opposite effect has also been reported: overexpression of hsa-miRNA-31-5p decreases levels of stathmin 1, a microtubule-depolymerizing molecule that leads to reduced chemosensitivity in ovarian cancer." (PMID 31467538, 2019). "In step with this mechanism of action, it was shown that high stathmin 1 expression was an adverse prognostic factor in ovarian cancer patients who received taxane-platinum combination chemotherapy." (PMID 29707144, 2018). "To evaluate if these epithelial lesions represent the precancerous state of ovarian cancer, we performed immunohistochemical localization of Pax8 and Stathmin 1, well-established markers of ovarian cancer precursor lesions and malignant disease." (PMID 27036037, 2016). "These pathological lesions expressed bonafide markers of ovarian cancer precursor lesions, Pax8 and Stathmin 1, and were presented with elevated mTOR signalling." (PMID 27036037, 2016). "Giving STMN1 a role in regulating the ovarian cancer chemoresponse, our data introduce miR-31 downregulation as the reason for STMN1 upregulation in response to TX treatment and resistance development." (PMID 25897432, 2015). "STMN1 level elevated in the chemoresistant ovarian cancer cells, KF-TX, compared with the parental, KF, ones." (PMID 25897432, 2015). "In order to investigate STMN1 regulation in response to TX in vitro in a subsequent study, we checked STMN1 expression in four ovarian cancer cell lines including TX-sensitive, parental KF cells and their TX-resistant counterparts, KF-TX cells." (PMID 25897432, 2015). "Then, functional studies were carried out to validate the regulatory mechanism of the expression of STMN1 by miR-31 in ovarian cancer cells and tissues." (PMID 25897432, 2015). "This study focused on the role of STMN1 in ovarian cancer chemoresponse and added a novel target to miR-31, through which miR-31 can regulate ovarian cancer chemoresponse." (PMID 25897432, 2015). "To evaluate the possible relationship between STMN1 expression and development of ovarian cancer chemoresistance, we examined the expression level of STMN1 in surgical specimens from 24 human ovarian cancer tissues." (PMID 25897432, 2015). "Herein, the immunohistochemical study indicated significant upregulation of the STMN1 in the ovarian cancer tissues defined as resistant tumors compared with those defined as responsive tumors." (PMID 25897432, 2015). "Notably, bioinformatics analysis and our ovarian tissue microarray data demonstrated a significant upregulation of STMN1 expression in ovarian cancer." (PMID 41361792, 2025). "The results demonstrated that, compared to the control group, the knockdown of STMN1 resulted in a significant reduction in both ovarian cancer cell proliferation and wound healing rate, further substantiating the critical role of STMN1 in ovarian cancer progression." (PMID 41361792, 2025). "Furthermore, STMN1 exhibited significantly elevated expression across various pathological stages and different subtypes of ovarian cancer." (PMID 41361792, 2025). "This inconsistency may be attributed to two factors: first, the microarrays of ovarian cancer used for IHC comprised various subtypes of ovarian cancer tissues, and STMN1 expression levels differed significantly among these subtypes." (PMID 41361792, 2025). "In this study, we found that STMN1 expression was significantly elevated in ovarian cancer tissues." (PMID 35186166, 2022). "Expression of STMN1 was measured by immunohistochemical staining in ovarian cancer tissues." (PMID 35186166, 2022). "To date, there have been several studies on STMN1 in ovarian cancer." (PMID 35186166, 2022). "These previous studies suggested that STMN1 may function as an oncogene and may be a potential target for the treatment of ovarian cancer." (PMID 35186166, 2022). "Immunohistochemistry showed an apparent overexpression of STMN1 in ovarian cancer." (PMID 35186166, 2022).
ovarian carcinoma (continued). "STMN1 promotes the proliferation and migration of ovarian cancer and is regulated by E2F1." (PMID 35186166, 2022). "STMN1 plays a crucial role in the proliferation and migration of ovarian cancer cells." (PMID 35186166, 2022). "STMN1 is overexpressed in ovarian cancer, and its high expression suggests a poor prognosis." (PMID 35186166, 2022). "STMN1 may be a novel indicator for the adverse prognosis of ovarian cancer patients and a promising target for the development of new treatments." (PMID 35186166, 2022). "Assessment of representative sections from the entire fallopian ducts of 11 patients with high risk of developing ovarian cancer revealed presence of cytoplasmic/nuclear βcatenin, LEF1, Pax8 and Stathmin 1-positive precursor lesions in all of the patients (SFigure 1)." (PMID 27588493, 2016). "Thus, we aimed to investigate the possible role of STMN1 in the chemoresponse in ovarian cancer and to study the regulatory mechanism of STMN1 expression under the effect of TX." (PMID 25897432, 2015). "Stage-dependent expression of STMN1 has also been noted in ovarian cancers." (PMID 25897432, 2015). "Taken together, these data indicate that loss of miR-31 expression may play an important role in the development of TX-resistance in ovarian cancer cells, probably by allowing the upregulation of STMN1." (PMID 25897432, 2015). "In this study, we tried to clarify the mechanistic role of STMN1 in ovarian cancer TX-resistance development, and revealed that STMN1 expression was significantly increased in the chemoresistant ovarian cancer tissues compared to the responsive ones by immunochemistry." (PMID 25897432, 2015). "Furthermore, miRNA profiling indicated that miR-31 downregulation is responsible for STMN1 upregulation in chemoresistant ovarian cancer cells." (PMID 25897432, 2015). "Since aberrant STMN1 expression might contribute to chemoresistance acquisition of ovarian cancer cells, exploration of the mechanism responsible for STMN1 upregulation might be of great importance to overcome chemoresistance." (PMID 25897432, 2015). "Furthermore, we demonstrated that STMN1 was regulated by E2F1, which might be an important mechanism through which STMN1 promotes proliferation in ovarian cancer cells." (PMID 35186166, 2022). "Moreover, we found that STMN1 could promote proliferation and migration in ovarian cancer cell lines." (PMID 35186166, 2022). "Furthermore, STMN1 promoted proliferation and migration in ovarian cancer cell lines." (PMID 35186166, 2022). "Thus, up-regulation of STMN1 might be one of the mechanisms of resistance to TX regulated by downregulation of miR-31 in ovarian cancer cells." (PMID 25897432, 2015). "This nanoparticle can improve the microtubule stability by interfering the expression of STMN1, thereby increasing the sensitivity to PTX, blocking cells in the G2/M phase, and ultimately leading to the death of ovarian cancer cells." (PMID 41361792, 2025). "However, the molecular mechanisms of STMN1 in ovarian cancer remain largely unknown." (PMID 35186166, 2022). "To determine the molecular mechanism of STMN1 in ovarian cancer, we performed gene set enrichment analysis (GSEA) to study mRNA sequencing data from 308 ovarian cancer patients in TCGA database (TCGA.OV.sampleMap/HiSeqV2_PANCAN)." (PMID 35186166, 2022). "Meanwhile, STMN1 has also been shown to be regulated by miR-193b, miR-31, and SIVA 1 in ovarian cancer." (PMID 35186166, 2022). "Therefore, STMN1 expression may be an indicator of poor prognosis in ovarian cancer patients." (PMID 35186166, 2022). "In this study, we demonstrated STMN1 as a potential clinical therapeutic marker in ovarian cancer and successfully designed and constructed a PEG-coated nano delivery system based on MPDA, which co-loaded with PTX and siRNA (STMN1) for the combined therapy of ovarian cancer." (PMID 41361792, 2025).
ovarian carcinoma (continued). "Second, we mapped out the negative relationship between STMN1 expression and miR-31 expression in ovarian cancer tissues." (PMID 25897432, 2015). "For instance miR-101, reported to act as inhibitor of autophagy in breast cancer by targeting STMN1, RAB5A, and ATG4D mRNAs, has been found downregulated also in ovarian cancer compared to normal tissue, and its reexpression exerted tumour-suppressive effects in ovarian carcinogenesis." (PMID 24877083, 2014). "In addition, there are no studies on the relationship between STMN1 expression and clinical factors in ovarian cancer." (PMID 35186166, 2022). "To date, it has not been confirmed whether STMN1 can promote the proliferation and migration of ovarian cancer cells in vitro." (PMID 35186166, 2022). "On the other side, introducing miR-31 to TX-resistant ovarian cancer cells not only reduced STMN1 expression followed by restoring chemoresponse, but also gave many signs that indicate the functional absence of STMN1, including MT stability and promotion of cell cycle progression from G2 to M phase." (PMID 25897432, 2015). "Thus, STMN1 may serve as a negative prognostic factor and possible target for the treatment of ovarian cancer patients." (PMID 35186166, 2022).
leukemia (15 papers, 2010 to 2024). A malignant (clonal) hematologic disorder, involving hematopoietic stem cells and characterized by the presence of primitive or atypical myeloid or lymphoid cells in the bone marrow and the blood. "Stathmin 1 overexpression has been observed in malignant hematopoietic cells, and stathmin 1 inhibition reportedly reduced the proliferation of leukemia cell lines." (PMID 35205115, 2022). "Aside from cell cycle regulation, roles of STMN1 in hematopoiesis have been addressed in leukemia cells." (PMID 33921319, 2021). "Studies also show elevated levels of STMN1 in many cancers including leukemia, whereas a dramatic decrease in STMN1 levels is found in hematopoietic cells upon differentiation along different lineages." (PMID 26466335, 2015). "In support of this hypothesis, phosphorylated WNK1 was shown to block insulin-stimulated mitosis, and GDP366-induced phosphorylation of STMN1 promoted cell cycle arrest and apoptosis in leukemia cells." (PMID 37305581, 2023). "In addition, leukemia-related oncogenes, including BCR-ABL1 and PML-RARα, have been associated with Stathmin 1 upregulation." (PMID 26356819, 2015). "A few additional proteins including minichromosome maintenance protein 2 and stathmin 1 have been linked to disease progression of other leukemias, but not directly to CLL and thus warrant further investigation in CLL." (PMID 20661426, 2010). "Notably, Stathmin 1 silencing reduces cell proliferation and clonogenicity of leukemia cell lines." (PMID 26356819, 2015). "STMN1, being one of the most over-expressed genes in AML, showed elevated expression levels in benzene-administered leukemic rats, confirming leukemia induction at the genetic level." (PMID 38139868, 2023).
glioma (14 papers, 2016 to 2025). A benign or malignant brain and spinal cord tumor that arises from glial cells (astrocytes, oligodendrocytes, ependymal cells). "Among TME-infiltrating male MG, we found cluster MG8 characterized by a high expression of genes encoding proliferation-related proteins (Stmn1, Tubb5, Tuba1b, Cdk1, and Top2a), which is consistent with the observed proliferation of MG within glioma TME, as previously reported." (PMID 33608526, 2021). "In U251 glioma cells, STMN1 knockdown inhibited both cyclin D1 and cyclin B expression while upregulating p21 expression, leading to cell cycle arrest in vitro." (PMID 40723207, 2025). "The expression of tumor protein translation control 1 antisense RNA 1 (TPT1-AS1) is upregulated in glioma cells, and the TPT1-AS1/miR-770-5p/stathmin 1 (STMN1) axis mediates autophagy in glioma cells, which is important for the targeted treatment of glioma." (PMID 38481525, 2024). "Among these ten hub nodes identified, RP11-363E7.4, miR-106a-5p, miR-3666, miR-665, miR-590-5p, and STMN1 facilitate cell death, whereas miR-4295 inhibits apoptosis in human glioma cell lines." (PMID 37514136, 2023). "LncRNA TPT1-AS1 inhibited glioma cell autophagy by decreasing the expression of miR-110-5p, and upregulating STMN1 expression promoted the proliferation of glioma cells." (PMID 34178684, 2021). "Stathmin also plays a role in neoangiogenesis, as high grade glioma-derived microvascular endothelial cells treated with STMN1 siRNA reduce cell viability, increase apoptosis rates and suppress significantly the endothelial cell migration." (PMID 26973435, 2016). "Expression of MELK and STMN1 was knocked out by specific siRNA transfection of U87MG glioma cell line." (PMID 26973435, 2016). "In addition, miR-770-5p has been found to be downregulated by lncRNA TPT1-AS1 and correspondingly upregulated the expression of STMN1, leading to promotion of the proliferation of Glioma cells." (PMID 32614631, 2020).
liver cancer (14 papers, 2014 to 2025). An epithelial or non-epithelial malignant neoplasm that arises from the liver. "STMN1 overexpression in liver cancer has previously been linked to invasion on the local level, early recurrence, and a bad prognosis, as well as facilitating the polyploid formation and other biological functions." (PMID 36127700, 2022). "Upregulation of the E2F1 and STMN1 proteins has been linked to poor outcomes in liver cancer patients." (PMID 36127700, 2022). "As a result, it needs to be seen if the STMN1 gene is linked to chemotherapeutic medications like vincristine in the treatment of liver cancer." (PMID 36127700, 2022). "Nomogram model results demonstrate that STMN1 expression can predict 1-, 3-, and 5-year survival rates, suggesting that STMN1 has the potential to be a useful diagnostic and prognostic biomarker in liver cancer." (PMID 36127700, 2022). "STMN1 expression is favorably linked with important immune checkpoint molecules, suggesting that it might be a potential target for liver cancer immunotherapy." (PMID 36127700, 2022). "We investigate the significance of STMN1 in diagnosing and predicting the prognosis of liver cancer, as well as its association with immune cell infiltration, immune cell biomarkers, immunological chemicals, and immune checkpoints, using data from a public scientific database." (PMID 36127700, 2022). "STMN1 has been found to be overexpressed in a variety of tumors, correlates with poor prognosis, and has been implicated as an important stimulator of metastasis in liver cancer." (PMID 34977159, 2021). "There is such a relationship between STMN1 gene and liver cancer, while PRDX1 is most correlated with endometrial cancer." (PMID 41403955, 2025). "Both VEGF-A and STMN1 are recognized as crucial biological markers that contribute to the advancement and poor prognosis of liver cancer." (PMID 40052130, 2025). "This study has demonstrated that STMN1 upregulation promotes the occurrence and development of liver cancer via activating a signaling pathway." (PMID 37754250, 2023). "In the present study, we explored the relationship between STMN1 in liver cancer function enrichment, immune infiltration, DNA methylation, and m6A, providing new evidence that STMN1 is a prognostic marker that can be exploited as a therapy target for HCC." (PMID 36127700, 2022). "We utilized the TIMER database to investigate the relationship between STMN1 expression and liver cancer immune cell biomarkers in order to learn more about STMN1’s function in the tumor immune microenvironment." (PMID 36127700, 2022). "Because STMN1 is highly expressed in liver cancer, we utilized the TCGA database to investigate the link between STMN1 expression and HCC clinicopathological features." (PMID 36127700, 2022). "Considering the potential carcinogenic role of STMN1 in liver cancer, STMN1 and these 8 immune checkpoint-related genes in HCC were investigated using the TIMER database." (PMID 36127700, 2022). "The transcription of STMN1 in the liver is downregulated by T3, suggesting that the lack of normal THR function will lead to the increased expression of STMN1 and the malignant growth of liver cancer." (PMID 36127700, 2022). "MST-312 drug activity was highly correlated with the STMN1 dependency in 19 liver cancer cell lines." (PMID 33922244, 2021). "In SNU-739, a liver cancer cell line, although there is a high level of FoxM1, the expression of STMN1 is very low, whereas in Colo-320 a CRC cell line, a low level of FoxM1 is accompanied with a high level of STMN1." (PMID 33526768, 2021). "We conclude that STMN1, an essential protein for tumorigenic growth and cell-cycle progression, is inhibited by T3 at the transcriptional level, reflecting the negative correlation between the expression patterns of these proteins in clinical liver cancer specimens." (PMID 27934948, 2016).
liver cancer (continued). "Subgroup analysis based on specific glycolysis markers revealed that higher expression of PKM2 (P < 0.001), STMN1 (P = 0.002), MCT4 (P < 0.001), GLUT1 (P = 0.025), HK-2 (P < 0.001), and CA9 (P < 0.001) was significantly correlated with poor OS in liver cancer." (PMID 38114977, 2023). "The results indicated that glycolysis markers, including PKM2, STMN1, MCT4, GLUT1, HK-2, CA9, and GLUT2, can serve as potential prognostic biomarkers and therapeutic targets for liver cancer." (PMID 38114977, 2023). "Meanwhile, the interaction of E2F1 and STMN1 was ascertained by ChIP assay and dual luciferase assay in HCC and liver cancer." (PMID 35186166, 2022). "Following that, we discovered that STMN1 was statistically significantly over-expressed in liver cancer tissues relative to noncancer tissues in six HCC datasets from the GEO and TCGA databases." (PMID 36127700, 2022). "Both these proteins are required for tumor cell migration in HCC, and STMN1 has been proposed as a negative prognostic marker in liver cancer." (PMID 29363612, 2018). "STMN1 affects the epithelial-mesenchymal transformation (EMT) of HCC cells by regulating the dynamic equilibrium of microtubules via the “STMN1 microtubule EMT” axis signal, suggesting that STMN1 might be a viable therapeutic target for limiting liver cancer metastasis." (PMID 36127700, 2022).